RN7SL842P (RNA, 7SL, cytoplasmic 842, pseudogene)
Gene: Miscellaneous RNA gene on chromosome 19 (14,588,357 to 14,588,656, forward strand). Ensembl gene ENSG00000243066.
Homologues: Orthologues: chimpanzee Metazoa_SRP (96% identical), macaque Metazoa_SRP (91% identical). Paralogues in human: RN7SL337P (94% identical), RN7SL1 (79% identical), RN7SL2 (79% identical), RN7SL3 (78% identical), RN7SL566P (78% identical), RN7SL296P (77% identical), RN7SL126P (77% identical), RN7SL14P (77% identical), RN7SL122P (76% identical), RN7SL230P (76% identical), RN7SL357P (76% identical), RN7SL478P (76% identical), and 702 more.